RNU6-654P (RNA, U6 small nuclear 654, pseudogene)
Gene: Small nuclear RNA gene on chromosome 11 (109,005,517 to 109,005,623, forward strand). Ensembl gene ENSG00000201243.
Homologues: Orthologues: macaque U6 (93% identical), mouse Gm24612 (91% identical), dog U6 (82% identical). Paralogues in human: RNU6-1181P (88% identical), RNU6-16P (87% identical), RNU6-1075P (85% identical), RNU6-12P (85% identical), RNU6-13P (85% identical), RNU6-32P (85% identical), RNU6-393P (85% identical), RNU6-41P (85% identical), RNU6-480P (85% identical), RNU6-820P (85% identical), RNU6-90P (85% identical), RNU6-945P (85% identical), and 1283 more.